TSC22D2 (TSC22 domain family member 2)
Description:
Reduces the level of nuclear PKM isoform M2 which results in repression of cyclin CCND1 transcription and reduced cell growth.
Synonyms: KIAA0669; TILZ4a; TILZ4b; TILZ4c
Tractability: PROTAC: ubiquitination databases record sites on it; its protein half-life has been measured.
Gene: Protein-coding gene on chromosome 3 (150,408,298 to 150,466,422, forward strand). Ensembl gene ENSG00000196428.
Subcellular location (Human Protein Atlas): Cytosol
Gene Ontology:
Molecular function: protein binding
Biological process: negative regulation of cell cycle; regulation of transcription by RNA polymerase II
Genetic constraint (gnomAD): Loss-of-function variants: 5 observed, 47.54 expected, observed/expected ratio (o/e) 0.11, 90% interval 0.054 to 0.22. The upper end of that interval is the gene's LOEUF score, 0.22, which puts it in group 1 of 6, group 1 being the genes least tolerant of losing a copy. Missense variants: 1,003 observed, 996.25 expected, observed/expected ratio (o/e) 1.01, 90% interval 0.95 to 1.06. Synonymous variants: 501 observed, 441.48 expected, observed/expected ratio (o/e) 1.13, 90% interval 1.05 to 1.22.
Homologues: Orthologues: chimpanzee TSC22D2 (99% identical), macaque TSC22D2 (96% identical), rabbit TSC22D2 (89% identical), guinea pig TSC22D2 (88% identical), pig TSC22D2 (87% identical), dog TSC22D2 (86% identical), mouse Tsc22d2 (84% identical), rat Tsc22d2 (83% identical), tropical clawed frog tsc22d2 (54% identical), Drosophila melanogaster bun (16% identical), Caenorhabditis elegans Y48C3A.12 (15% identical), Caenorhabditis elegans tsct-1 (10% identical). Paralogues in human: TSC22D1 (30% identical), TSC22D4 (17% identical), TSC22D3 (11% identical).
Diseases named in the same sentence as TSC22D2 in open-access papers:
TSC22D2 is named in the same sentence as 10 diseases in open-access papers, as found by Europe PMC text mining. Sharing a sentence is not in itself a finding about the gene and the disease. The quoted sentences say what the papers report.
atherosclerosis (2 papers, 2022 to 2025). A disease characterized by the build-up of fatty material and calcium deposition in the arterial wall resulting in partial or complete occlusion of the arterial lumen. "Of the 25 shared novel atherosclerosis loci with evidence of colocalization, 7 analyses strongly colocalized with PRPA ≥0.80 (nearest gene: BNC2, SCAI, TSC22D2, SRRM1, ABCB11, PRRX2)." (PMID 40313769, 2025).
colorectal cancer (1 paper, 2023). A primary or metastatic malignant neoplasm that affects the colon or rectum. "The expression of TSC22D2 was reported to be significantly downregulated in colorectal cancer, while we found that the expression of TSC22D2 was significantly higher in pancreatic cancer tissues/cells compared to the normal tissues/cells using public databases and experiments." (PMID 36894917, 2023). "However, in colorectal cancer, TSC22D2 was considered as a tumor suppressor gene, and overexpressed TSC22D2 inhibited tumor growth." (PMID 36894917, 2023).
Obesity (1 paper, 2021). Accumulation of substantial excess body fat. "For example, the molecular functional mechanisms of CEP120, TSC22D2, Al090771.1 and LHX2 have not been yet linked to obesity, fat distribution and obesity comorbidities." (PMID 34072523, 2021).
pancreatic cancer (1 paper, 2023). "Data from GEPIA showed that TSC22D2 gene expression was significantly upregulated in pancreatic cancer tissues (n = 179) than that in normal tissues (n = 171) (p < 0.001)." (PMID 36894917, 2023). "The mRNA levels of TSC22D2 were increased among all four pancreatic cancer cells as compared to HPNE control." (PMID 36894917, 2023). "The results showed that TSC22D2 was significantly up-regulated in pancreatic cancer tissues compared with controls." (PMID 36894917, 2023). "Data from public databases and our own experiments showed that TSC22D2 expression was significantly higher in pancreatic cancer tissues/cells compared to normal tissues/cells." (PMID 36894917, 2023). "The higher expression of TSC22D2 in the pancreatic cancer tissues/cells was also confirmed by the public databases and experiments." (PMID 36894917, 2023). "In addition, we detected the expression of TSC22D2 in pancreatic cancer tissues and paired para-tumor normal tissues by immunohistochemistry (IHC) staining." (PMID 36894917, 2023). "Thus, an independent prognostic predictor of PAAD is TSC22D2 high expression, and TSC22D2 expression was also higher in pancreatic cancer tissues/cells than in normal tissues/cells." (PMID 36894917, 2023). "Our western blot results revealed that pancreatic cancer cell lines (BxPC-3, PANC-1, MIA PaCa-2) had higher TSC22D2 protein expression than hTERT-HPNE." (PMID 36894917, 2023).
cancer (3 papers, 2021 to 2025). A tumor composed of atypical neoplastic, often pleomorphic cells that invade other tissues. "Previous research identified that TSC22D2 was a novel cancer-associated gene in a rare multi-cancer family." (PMID 36894917, 2023). "Furthermore, the DepMap database suggests that there is a notable codependence in cell viability between WNK1, NRBP1, and TSC22D2 in certain cancer cell lines, consistent with these components operating within a common pathway, and this was also highlighted in another recent study." (PMID 40668933, 2025). "Thus, TSC22D2 plays a controversial role in cancers, especially in PAAD." (PMID 36894917, 2023).
tumor (2 papers, 2022 to 2023). "The DNAJC1 and TSC22D2 genes were related to a large number of genes to suppress cell proliferation in tumor processes and adverse conditions." (PMID 35629975, 2022). "High expression of TSC22D2 was also related to a significantly higher AJCC tumor stage." (PMID 36894917, 2023).
infection (1 paper, 2021). The state of being infected such as from the introduction of a foreign agent such as serum, vaccine, antigenic substance or organism. "The transcription factors GABPA, ZNF579, SP110, and TSC22D2 were also induced after infection." (PMID 34777295, 2021).
TSC22D2 also shares sentences with these, for which no sentence is quoted: breast carcinoma (1 paper); Cirrhosis (1); hepatocellular carcinoma (1).